BAX (BCL2 associated X, apoptosis regulator)
Diseases named in the same sentence as BAX in open-access papers (continued):
Sharing a sentence is not in itself a finding about the gene and the disease.
tumor (continued). "TP63, functioning as a central regulator of squamous epithelial differentiation, promotes tumor progression through dual mechanisms—activating proliferative pathways (NOTCH and Wnt/β-catenin signaling) while inhibiting apoptosis mediators like BAX and PUMA." (PMID 40508204, 2025). "The expression levels of MCM3, BCL2, and N-cadherin increased, whereas those of cyclin A, BAX, and E-cadherin decreased in ZMIZ2-overexpressing tumor tissues." (PMID 41502508, 2025). "The uniform manifold approximation and projection (UMAP) diagram revealed that BAX, IL1B, and TNF were predominantly expressed in epithelial cells and macrophages in tumor tissues." (PMID 39744500, 2025). "This pro-apoptotic phenotype correlated with upregulation of pro-apoptotic BAX, and downregulation of anti-apoptotic BCL-2, indicating RSF1 sustains tumor cell survival by regulating the mitochondrial apoptotic pathway." (PMID 40862741, 2025). "The effect of the four tested treatment groups was evaluated on the key apoptotic protein markers (BAX, BCL-2, and caspase 3,7, 8, and) 9 which are vital for stopping tumor progression and the activation of the intrinsic and/or extrinsic apoptotic pathways." (PMID 40218923, 2025). "LncRNA MALAT1 and HOTAIR are highly expressed in LUAD, promoting tumor cell proliferation, and inhibiting apoptosis by regulating cell cycle proteins and apoptosis-related molecules (such as BCL-2 and BAX)." (PMID 39834603, 2025). "This signature, comprising TRP53BP1, P21, BAX, CYCLIN D1, OCT-4, and NANOG, appears to influence tumor response to radiation." (PMID 39594660, 2024). "To further elucidate the molecular mechanism underlying the effect of ailanthone against HCC in vivo, we performed IHC analysis to investigate the protein expression of LC3, PINK1, PRKN, BAX, and BAK1 in tumour tissues." (PMID 39723259, 2024). "RT-PCR analysis of xenograft tumor lysates revealed that the expression levels of E-cad, Slug, ITGB8, ITGB1, PCNA, and BAX showed a similar pattern to those observed in vitro, and Western blot results also confirmed these findings." (PMID 39459033, 2024). "The BAX gene had different correlation coefficients in the three tumor types, while the PIK3CA gene had different correlation coefficients in two tumor types." (PMID 38463169, 2024). "The results show that BAX and BCL2L1 were significantly (p < 0.001) higher in the tumor tissue than in the normal tissue when comparisons were made, whereas NFKBIA was significantly (p < 0.001) higher in the normal than in the cancer tissue." (PMID 38542508, 2024). "The analysis of gene expression based on tumor size showed that in macroadenomas, both VDAC1 and BAX were decreased (median RQ = 0.49; p <0.001 and median RQ = 0.43; p <0.001, respectively)." (PMID 39449743, 2024). "At the molecular level, tumor tissues of the HFD group mice exhibited high expression of Ki-67 and vimentin, but low expression of BAX." (PMID 38319449, 2024). "Thus, we hypothesized that MAPK3 may regulate tumor apoptosis and autophagy by affecting BAX." (PMID 38800011, 2024). "Astragalosidei can induce the apoptosis of various tumor cells by decreasing the expression level of BCL-2 and increasing the expression level of BAX." (PMID 39323640, 2024).
tumor (continued). "In SNU-1196-GR-derived tumor tissues, the combination of capivasertib and GEM enhanced hENT1 expression and reduced BAX Ser184 phosphorylation." (PMID 37324940, 2023). "The induction of apoptosis was also confirmed by the ratio of the expression levels of the BAX and BCL-2 genes, which was higher than 1 in tumor cells treated with CIMVs-TRAIL." (PMID 36661524, 2023). "Hypoxia in a tumor cell is related to apoptosis as hypoxia-inducible factor-alpha (HIF-α) regulates the apoptotic genes (BCL-2, BAX, caspase 3, caspase 8) as well as a survival signaling pathway, i.e., NF-kB." (PMID 36715825, 2023). "Unlike miR-145-5p target genes, p21WAF1 transcript was upregulated as it frequently occurs upon elevated expression of tumor suppressor genes and concomitantly, we observed the induction of the expression of some apoptotic targets such as CHOP, BAX, and NOXA." (PMID 37598177, 2023). "Then, tumor growth rate, tumor necrotic area, the expression of the apoptosis-related genes CASP8, BCL-2, and BAX and the level of CASP8 protein were analyzed." (PMID 36661524, 2023). "The expression of pro-apoptotic markers (CASP and BAX) and anti-apoptotic proteins (BCL-2 and BCL-XL) is used as an indicator of apoptosis induction in tumor cells." (PMID 37188770, 2023). "As expected, our gene expression results demonstrated that the triple-drug combination (TME) significantly reduced the levels of BCL2 and enhanced the expression levels of BAX, BAD, caspase-9, 8 and 3 when compared to that of tumor-control group (p < 0.0001)." (PMID 37025487, 2023). "Inhibition of SMG1, independent of TORK and DNA‐PK, appeared to be the prime mode of CC‐115‐induced caspase and BAX‐ and BAK‐dependent cell death in certain tumor cells." (PMID 36400430, 2023). "There were more apoptotic cells in QRHXF group's tumor tissues, and QRHXF treatment increased BAX and cleaved-caspased 3 levels but decreased Bcl-2 levels." (PMID 36860928, 2023). "BCL2, a class of anti-apoptotic proteins, modulates apoptosis and promotes survival in tumor cells; While, the pro-apoptotic proteins BAX, and BAD, residing on the mitochondrial membrane is usually downregulated in tumor cells." (PMID 37025487, 2023). "ABCB1, BAX, BCL2, FADD, FAS, and several tumour protein families were identified as the genes responsible for such findings." (PMID 35884999, 2022). "The expression levels of BAX (p = 0.0017), ERH (p = 0.0067), APC (p = 0.0416), and CNBP (p = 0.0244) were significantly higher in tumor tissues of the NBL group than in the control group." (PMID 35991559, 2022). "Meanwhile, treatment with BDMC up-regulated the expressions of BAX and cleaved caspase-3, while it down-regulated the protein expressions of Bcl-2 and XIAP in the tumor tissues compared with the control group." (PMID 35008959, 2022). "For the cirReNET we built, there were many targeted genes involved in the mechanism of tumor genesis, such as AKT1, ErbB2, ITGB7, BAX, MAPK, FBXL12, CCL7 and so on." (PMID 35611168, 2022). "We have also tested the mRNA expression of apoptosis-relevant genes (BAX, BCL-2 and CASP3) in tumor tissues of our model mice, and a TUNEL assay in tissue slices, which revealed an elevated apoptosis tendency in FBXO17-overexpressed mice implanted tumor." (PMID 36035375, 2022).
tumor (continued). "Consistently with transcriptomic analysis, we also observed marked differences in the mRNA levels of BAX, HRK, CDK6, CDK14, and BCL2 between the sgCONT and NOXAKO tumor cells after co-incubated with CD19 CAR T cells." (PMID 35370290, 2022). "Using quantitative Bcl-2 protein profiles of BAK, BAX, BCL2, BCL(X)L, and MCL1 as model input for DR_MOMP, we were able to calculate the sensitivity of individual tumor cells to the process of mitochondrial apoptosis initiation." (PMID 34754079, 2022). "The genes involved in tumor suppression (e.g., TGFBR2), cell proliferation, DNA repair (e.g., MSH3 and MSH6), apoptosis (e.g., BAX), etc., contain repetitive sequences in the coding regions, and alterations tend to develop in these regions." (PMID 34185173, 2021). "The network consists of a system of ordinary differential equations (ODEs) involving eight variables: concentrations of STAT1, STAT3, Bcl-2, BAX, IFN-β, JAK2 and DDP and tumour volume." (PMID 34631119, 2021). "It is already known that CDKN1A, BAX, CASP9 and E-cadherine are involved in tumor growth suppression and apoptosis." (PMID 34281228, 2021). "But how these patient-specific differences of BAX and SMAC expression affect the properties of the bistable switch, such as the amplitude of caspase activation and the sensitivity of tumour cells to DNA damaging drugs, is not well understood." (PMID 33558564, 2021). "The anticancer effect of ATO is mainly through upregulating the apoptosis promoter gene BAX and downregulating the apoptosis inhibitor gene BCL-2 to induce tumor cell apoptosis." (PMID 34458205, 2021). "Subsequently, we performed the mRNA and protein detection of proliferation markers (CYCLIN B1, PCNA, and KI-67) and apoptosis markers (BAX and BCL2) in the tumor tissues of each mice group." (PMID 34447747, 2021). "Complex 14 was able to selectively inhibit MCL-1 and disrupt MCL-1/BAX and MCL-1/BAK complexes in tumor cells, inducing BAX/BAK-dependent apoptosis in tumor cells." (PMID 33883020, 2021). "We further performed western blotting to detect the protein expression of JWA, CDK12, Bcl-2, BAX, Caspase-3, and PCNA in xenograft tumor tissues." (PMID 34686673, 2021). "This shift in prooxidant enzyme and antioxidant enzyme balance may cause the imbalance of proapoptotic (BAX and BAD) and antiapoptotic genes (BCL2 and BCL2L1), resulting in a tumor microenvironment which is in favor of surviving and resistant to apoptosis in Tg tumor." (PMID 33456675, 2020). "Tumor samples from the 5 and 10 mg/kg DOXY treated groups showed significant increases in BAX (2.05-fold and 2.98-fold) and caspase 3 (2.33-fold and 3.17-fold) expressions." (PMID 32679837, 2020). "Cancer development due to dMMR/MSI is triggered by mutations in genes that contain microsatellites and are important for tumor suppression, such as TGFbeta RII, IGFIIR, BAX, hMSH6, and hMSH3 genes." (PMID 33182707, 2020). "The results show a strong correlation between BAX and BAK localization in tumor and non-tumor samples." (PMID 32486514, 2020). "We found ten potential prognostic genes, including eight tumor suppressor and/or driver genes (VEGFA, CCND1, BAX, IL7R, SHC1, FLT1, IL7, and JAK3), as well as two chemokines (CXCL9 and CXCL10)." (PMID 31661791, 2019). "To show the activity of strophanthidin as an anticancer agent, we determined the expression of proteins involved in apoptosis such as BAX, proto-oncogenes like c-Myc, caspases, and PARP in tumor cells." (PMID 32010609, 2019).
tumor (continued). "Knockdown of AKT3-S472 in TNBC displays an enhanced tumor growth in vivo by downregulating Bim via activation of the MAPK/ERK pathway and therefore inhibition of BAX." (PMID 31752925, 2019). "Proteins like BAX and BAK, with proapoptotic activity, were upregulated in the tissue and showed suppressed expression of antiapoptotic proteins in culture tumor cells when treated with silibinin flavonoid (SIL)." (PMID 29681978, 2018). "Beyond targeting anti-apoptotic BCL-2 proteins, increasing interest has centred on developing drugs that directly activate BAX and BAK in order to kill tumour cells." (PMID 29769323, 2018). "Of the 4 lapatinib-treated tumours, 2 showed an increase in MCL-1 and a decrease in BAX mRNA levels post-treatment, similar to the changes observed in the SKBR3-L cells." (PMID 30305055, 2018). "In summary, this study highlights the ‘BAX/BAK-like’ protein BOK as a prognostic marker in CRC, with increased BOK tumour levels indicating unfavourable clinical outcome in Stage II/III CRC patients." (PMID 29374142, 2018). "Along these lines, a recent study has shown that a BAX-activating molecule, BTSA1, shows potent anti-tumour effects on human acute myeloid leukaemia (AML) xenografts in the absence of toxicity." (PMID 29769323, 2018). "Of 4 tumours treated with trastuzumab plus chemotherapy, an increase in MCL-1 and decrease in BAX was observed in 1 case." (PMID 30305055, 2018). "Quercetin and green tea reduced tumor growth in HL-60 xenografts accompanied by decreased expression of anti-apoptotic proteins, BCL-2, BCL-XL and MCL-1 and increased expression of BAX, a pro-apoptotic protein." (PMID 29472583, 2018). "Overexpression of HSP70 can inhibit external and internal apoptosis pathway by binding to BAX and death receptor DR4 and DR5, but it plays the role of a tumor specific antigen which is highly immunogenic." (PMID 29850009, 2018). "The upregulation of BAX and PUMA after SFN treatment has been previously demonstrated in different tumours." (PMID 28864908, 2018). "Immunohistochemical analysis of the tissue micro array derived from these patients established the functional correlation between the decreased expression of tumor suppressive miRNAs and their target oncogenes: ERBB2, EGFR, EPHA2, BAX, GNA12, GNA13, and JUN." (PMID 28740575, 2017). "Enhanced expression of BAX, cytochrome C, and PARP was observed in dB/DCN-treated A549 tumor tissue compared to PBS- or dB-treated tumor tissue." (PMID 29100340, 2017). "The Western blot analyses also revealed that the pro-apoptotic proteins BAX and BIM, apoptosis marker PARP, and normal differentiation marker E-cadherin were increased in 2HF-treated tumor tissue lysates as compared to untreated controls." (PMID 29088842, 2017). "Here we revealed that re-expression of RASSF1A promotes its tumor suppressive function through the activation of pro-apoptotic and anti-proliferative YAP1 target genes (e.g. BAX and CDNK1A) in TREx293 cells." (PMID 29179447, 2017). "Knock down of Beclin1 suppressed: drug-induced mitophagy; the activation of the toxic BH3 domain proteins BAX and BAK; and tumor cell killing." (PMID 27379204, 2016). "Over-expression of BCL-XL or knock down of BAX, BIM, BAD or apoptosis inducing factor (AIF) protected tumor cells." (PMID 26981780, 2016). "hPEPD-G278D also up regulated BAX, down regulated BCL-2 and activated caspase-3 in the tumor tissues, which is consistent with marked tumor regression upon hPEPD-G278D treatment." (PMID 27286447, 2016).
tumor (continued). "Inhibition of AXL reversed chemoresistance by decreasing expression of the anti-apoptotic proteins BCL-2, BCL-XL, MCL1 and survivin in tumor cells and activated pro-apoptotic proteins BAD, BAX, BCL-2, BAK and PUMA." (PMID 26328272, 2015). "The decreased expression of BAX, as well as the increased expression of BCL-w, was also confirmed by immunohistochemical analysis on tumor biopsies." (PMID 25644060, 2015). "We also observed increased apoptosis in G31P treated tumor using TUNEL staining, supported by immunoblotting analyses of apoptotic proteins such as PARP, Caspase-8, BAX, and Bcl-2." (PMID 26087179, 2015). "When taken together, these data indicate that G6 treatment reduces tumor volume, in part, via increased expression of BIM and BAX." (PMID 25162558, 2014). "Thus, inactivation of TGFBR2 or BAX may contribute to tumor progression." (PMID 21949851, 2011). "However, as commented by the authors, this hypothesis does not always hold true, since it is well recognized that MSI, which is known to cause inactivation of a number of tumor suppressors (including TGFBR2, BAX, and many others), is associated with better patient outcome." (PMID 22050898, 2011). "Polymerase chain reaction (PCR) was done to amplify microsatellite sequences at mononucleotide BAT – 26, BAT – 40, TGFβ RII, IGFIIR, hMSH3, BAX and dinucleotide D2S123, D9S283, D9S1851 and D18S58 loci in blood (control) and tumor DNA." (PMID 15647110, 2005). "BAX-negative tumours, therefore, may be less susceptible to apoptosis." (PMID 12592374, 2003). "SFXN1 appears to be functionally linked with cell survival and growth promotion genes (AKT1, BCL2, MTOR) and pro-apoptotic components (BAX, CASP3), indicating its dual role in maintaining mitochondrial homeostasis and regulating cell fate decisions in tumor cells." (PMID 41399448, 2026). "PTEN is a classic tumor suppressor gene while BCL2, BAX and Caspase-3 are regulators of apoptosis." (PMID 40457415, 2025). "These possibilities highlight the need for further investigation into the non-canonical roles of BAX in tumor biology, particularly within metabolically reprogrammed and immunosuppressive niches." (PMID 40382614, 2025).